MTOR (mechanistic target of rapamycin kinase)
Diseases named in the same sentence as MTOR in open-access papers (continued):
Sharing a sentence is not in itself a finding about the gene and the disease.
ovarian carcinoma (continued). "Restoration of miR-199a-5p expression in ovarian cancer cells has been shown to increase sensitivity to cisplatin, both through targeting mTOR and by targeting CD44, thereby reducing ovarian cancer stem cell levels." (PMID 26717044, 2016). "Together, these results further confirm that everolimus inhibits tumor growth of ovarian cancer via targeting of the mTOR/S6 pathway and activation of apoptosis in vivo, regardless of obesity status." (PMID 26959121, 2016). "Phosphorylation of mTOR expression has been found in 55% of ovarian cancers, and high levels of mTOR signaling have been found to be an independent biomarker of poor survival in epithelial ovarian cancer." (PMID 26959121, 2016). "We next evaluated the effect of PI3K/mTOR and IKKβ inhibition alone and in combination on proliferation and survival of ovarian cancer cells." (PMID 26657155, 2016). "Treatment with mTOR inhibitors reduced human ovarian cancer cell viability, proliferation and colony forming ability." (PMID 27036037, 2016). "We and others have shown that overactivation of mTOR signalling occurs in approximately 80% of human ovarian carcinomas." (PMID 27036037, 2016). "It was confirmed that uPA promoted VM formation through AKT/mTOR/MMP-2/Laminin5γ2 signal pathway in ovarian cancer." (PMID 26992227, 2016). "Synthetic mTOR blockers were able to inhibit the proliferation of mouse ovarian granulosa cell tumors and human ovarian cancer cells." (PMID 27886120, 2016). "Several clinical trials have been performed in ovarian cancer patients targeting the mTOR pathway, including monotherapies as well as combination with standard first line therapy, however, resulting in limited benefit." (PMID 27090655, 2016). "For example, single-agent mTOR inhibition therapy, such as temsirolimus, has shown modest activity in epithelial ovarian cancer." (PMID 27983698, 2016). "Simvastatin significantly inhibited cellular proliferation, induced cell cycle G1 arrest and apoptosis, and caused cellular stress via reduction in the enzymatic activity of HMGCR and inhibition of the MAPK and mTOR pathways in ovarian cancer cells." (PMID 26503475, 2016). "All of these results suggested that uPA was a positive mediator for VM formation in ovarian cancer via AKT/mTOR/MMP-2/Laminin5γ2 signal pathway." (PMID 26992227, 2016). "mTOR activity is generally enhanced in epithelial ovarian cancer and numerous clinical trials are currently in place using mTOR inhibitors in ovarian cancer." (PMID 27533079, 2016). "Activation of PI3K/Akt/mTOR signaling pathway promotes ovarian cancer development by inhibiting autophagy." (PMID 27825125, 2016). "Everolimus inhibits mTOR kinase activity and its downstream targets by acting on mTORC1 and has anti-tumorigenic activity in ovarian cancer." (PMID 26959121, 2016). "Inhibition of IKKβ augmented the efficacy of PI3K/mTOR inhibition in suppressing clonogenic growth of ovarian cancer cells with GAB2 overexpression." (PMID 26657155, 2016). "Several phase I–II clinical trials are now ongoing with mTOR inhibitors in patients with ovarian cancer." (PMID 26959121, 2016). "In mouse ovary, constitutive activation of PI3K/mTOR signalling results in the development of similar tumours confirming the role of this pathway in pathogenesis of ovarian cancer." (PMID 27036037, 2016). "They suppressed LRP6 expression, inhibited both Wnt/β-catenin and mTOR/STAT3 signaling in ovarian cancer ascites cells and chemoresistant cell lines, and displayed potent in vitro anti-proliferative effects." (PMID 27888804, 2016). "Together, these results suggested inhibition of PI3K/AKT/mTOR signaling at least in part account for the strong inhibitory effect on the growth of disseminated ovarian cancer cells by combined use of BKM120 and Olaparib." (PMID 26909613, 2016).
ovarian carcinoma (continued). "Niclosamide has been shown to be anti-proliferative against prostate, colorectal, lung, breast, and ovarian cancers, and myelogenous leukemia by inhibiting multiple pathways (Wnt/β-catenin, Notch, NF-kB, mTOR, and STAT3) and inducing mitochondrial uncoupling." (PMID 27888804, 2016). "As cisplatin is known to induce apoptotic cell death, several studies have reported on the role of the PI3K/AKT/mTOR signaling pathway in cisplatin sensitivity/apoptosis in different cell and cancer types (e.g., kidney cells and ovarian cancer)." (PMID 27602956, 2016). "Niclosamide reduced STAT3 and mTOR downstream protein expression in ascites cells from ovarian cancer patients." (PMID 27888804, 2016). "In this study, we describe the anti-tumorigenic efficacy of everolimus attributed to inhibition of mTOR signaling in ovarian cancer, including obesity-driven tumors." (PMID 26959121, 2016). "These pathological lesions expressed bonafide markers of ovarian cancer precursor lesions, Pax8 and Stathmin 1, and were presented with elevated mTOR signalling." (PMID 27036037, 2016). "We observed similar effects of lactate and glutamine on mTOR signaling in lactate-avid SiHa ovarian cancer cells, which have been extensively used to study metabolic symbiosis." (PMID 27134166, 2016). "MiR-497 and mTOR/p70S6K1 were inversely correlated in ovarian cancer tissues, while mTOR and p70S6K1 were positively correlated." (PMID 26238185, 2015). "Taken together, these results showed lower expression levels of miR-497 were inversely correlated with mTOR/p70S6K1 levels of ovarian cancer patients." (PMID 26238185, 2015). "Previous studies show mTOR activity was suppressed by DHA in ovarian cancer cells, and in rhabdomyosarcoma cells." (PMID 25799586, 2015). "The novel Gab2/PI3K/Zeb1 pathway can be targeted by PI3K and mammalian target of rapamycin (mTOR) inhibitors and can be potentially used to treat Gab2-driven ovarian cancer in combination with standard chemotherapy." (PMID 26095858, 2015). "First, we treated the three ovarian cancer cell lines with different concentrations of rapamycin (0, 0.1, 1.0, and 10 nmol/l), an mTOR inhibitor, in regular media for 24 h." (PMID 26045471, 2015). "Knockdown of endogenous mTOR and p70S6K1 exerted a similar effect as overexpression of miR-497 on decreasing resistance of ovarian cancer cells." (PMID 26238185, 2015). "Several natural compounds or their synthetic analogs, such as isoflavones and bisflavones, have been demonstrated to overcome cisplatin resistance in ovarian carcinoma through suppression of the PI3K/AKT/mTOR signaling." (PMID 26325371, 2015). "We found that the expression levels of mTOR and p70S6K1 were upregulated in cisplatin-resistant ovarian cancer cells (A2780/CP and SKOV3/CP) compared with cisplatin-sensitive cells (A2780 and SKOV3)." (PMID 26238185, 2015). "Fibroblast growth factor 2 (FGF2), which is a member of the FGF family, induces ovarian cancer cell invasion by the activation of the PI3K/Akt/mammalian target Of rapamycin (mTOR) and MAPK/extracellular signal-regulated kinase (ERK) signaling pathways." (PMID 26356073, 2015). "In conclusion, the present study provides the first detailed comprehensive analysis of glutamine on cell proliferation, glycolysis, cell cycle and apoptosis, cell stress, energy flux and mTOR/S6 signaling pathways in ovarian cancer cells." (PMID 26045471, 2015). "AKT2 amplification, potentially predicting sensitivity to AKT/MTOR inhibitors, was highly amplified in breast, lung and ovarian cancer samples in our dataset." (PMID 25889064, 2015). "Here, we demonstrated that high leptin levels, as observed in the obese population, indeed activate the PI3K/AKT/mTOR signaling pathway in ovarian cancer cells (e.g., SKOV3 and UCI101)." (PMID 26053184, 2015). "Downregulation of miR-497 contributes to high levels of mTOR and p70S6K1, which makes ovarian cancer cells resistant to cisplatin-based chemotherapy." (PMID 26238185, 2015).
ovarian carcinoma (continued). "Our results demonstrated that mTOR and p70S6K1 are two direct targets of miR-497, highlighting the potential role of miR-497 downregulation for ovarian cancer cells to develop a chemoresistance phenotype." (PMID 26238185, 2015). "The PI3K/AKT/mTOR pathway is a well-known pathway involved in ovarian cancer carcinogenesis and mTOR as a drug target (e.g.: Rapamycin, Everolimus, and Temsirolimus) is being investigated in clinical trials." (PMID 24655477, 2014). "This novel therapeutic agent NVP-BEZ235, which targets both PI3K and mTOR, has been shown to inhibit cell growth of cisplatin-sensitive as well as cisplatin-resistant human ovarian carcinoma cell lines." (PMID 24526917, 2014). "The PI3K/Akt/mTOR signaling pathway is one of the most frequently deregulated signaling pathways in solid tumors including ovarian cancers, as compiled in the Cancer Genome Atlas, and has a functional role in drug resistance." (PMID 25061503, 2014). "In ovarian cancer co-targeting of the PI3K/mTOR and RAS/MEK pathway demonstrated a synergistic inhibition of proliferation and induction of cell death." (PMID 25401499, 2014). "This is the rationale for the use of mTOR inhibitors in ongoing clinical trials for the treatment of ovarian cancers." (PMID 25136588, 2014). "Emerging basic research, preclinical and clinical findings support the importance of p70 S6 kinase (p70S6K), a downstream effector of mammalian target of rapamycin (mTOR), in the progression of ovarian cancer." (PMID 25193855, 2014). "The mTOR inhibitor RAD001 upregulated Mirk expression in ovarian cancer cells grown under adherent conditions and sensitized them to Mirk inhibitors." (PMID 25061503, 2014). "Recently, we demonstrated that thioridazine dramatically suppressed cell growth by inducing apoptosis, and that its angiostatic effects were mediated by the inhibition of FAK/mTOR signaling in ovarian cancer cells in vitro." (PMID 24952635, 2014). "A recent in vitro study indicated the role of IGF1 in enhancing ovarian cancer cell proliferation through PI3K/Akt/mTOR signalling." (PMID 24237932, 2013). "With the recent release of the Cancer Genome Atlas for ovarian cancer, it was shown that the PI3K/AKT/mTOR pathway was one of the most frequently mutated or altered pathways in patients’ tumors." (PMID 23591839, 2013). "While PI3K/AKT/mTOR inhibitors are in trials for breast cancer and endometrial cancer, there have been limited clinical uses thus far in ovarian cancer." (PMID 23591839, 2013). "In this review, the focus will be on recent research implicating the PI3K/AKT/mTOR pathway in ovarian cancer progression and tumorigenesis." (PMID 23591839, 2013). "The role of the PI3K/Akt/mTOR pathway in ovarian cancer is foreshadowed by its role in protecting the primordial follicles from destruction during normal oocyte maturation." (PMID 23591839, 2013). "This review focuses on recent research on the PI3K/AKT/mTOR pathway and its role in the progression and tumorigensis of ovarian cancer." (PMID 23591839, 2013). "The current data support a crucial role for FGF2 in the down-regulation of E-cadherin in ovarian carcinoma cells via the PI3K/Akt/mTOR and MAPK/ERK signaling pathways." (PMID 23554977, 2013). "When brought together, a picture begins to emerge on how the PI3K/AKT/mTOR pathway is playing a key role in invasion for ovarian cancer." (PMID 23591839, 2013). "The role of the PI3K/AKT/mTOR pathway in terms of proliferation and progression of ovarian cancer is extremely complex." (PMID 23591839, 2013). "Mutations in the p110 subunit of PI3K, called PIK3CA, are often responsible for activation of the phosphatidylinositol 3-kinase (PI3K)/AKT/mammalian target of rapamycin (mTOR) pathway and have been detected in 12% of ovarian cancers." (PMID 24063014, 2013). "miRNA-21 also acts on ovarian cancer via the PI3K/AKT/mTOR pathway by suppressing PTEN, and is even activated by AKT in hypoxic conditions to induce survival." (PMID 23591839, 2013).
ovarian carcinoma (continued). "Through these various changes, the PI3K/AKT/mTOR pathway has demonstrated to play a key role in ovarian cancer tumorigenesis, progression, and chemotherapy resistance." (PMID 23591839, 2013). "Taken together, these results indicate that the MAPK/ERK and PI3K/Akt/mTOR pathways are involved in FGF2-induced ovarian cancer cell invasion." (PMID 23554977, 2013). "In summary, the present study indicates that miR-199a contributes to the reversal of cisplatin resistance by blocking the expression of mTOR in cisplatin-resistant ovarian cancer cells." (PMID 24137412, 2013). "One of the first reports on clinical use of a PI3K/AKT/mTOR inhibitor in ovarian cancer looked at the utility of the dual-targeting strategy involving PI3K/AKT/mTOR and RAF/MEK/ERK pathways." (PMID 23591839, 2013). "Raptor has a similar effect on proliferation as mTOR siRNA knockdown, thereby indicating that mTORC1 is more important in cell proliferation for ovarian cancer." (PMID 23591839, 2013). "Researching how the PI3K/AKT/mTOR pathway affects the progression and tumorigensis of ovarian cancer will hopefully lead to new therapies that will increase survival for women." (PMID 23591839, 2013). "In a study that analyzed the ascites fluid of 88 patients with advanced ovarian cancer, the mutational status and phosphorylation status of members of the PI3K/AKT/mTOR pathway were analyzed." (PMID 23591839, 2013). "Robust pre-clinical models have been established for studying the PI3K/AKT/mTOR pathway in ovarian cancer." (PMID 23591839, 2013). "For instance, TNFα, a cytokine involved in ovarian cancer growth and metastasis, is a potent activator of NF-kB, which in turn activates the anti-apoptotic and anti-autophagic Akt/mTOR pathway." (PMID 22974323, 2012). "Of note, ARH1 protein has recently been shown to up-regulate autophagy (through inhibition of the mTOR pathway) and to induce autophagy-dependent dormancy in ovarian cancer cells." (PMID 22974323, 2012). "The components of PI3K/AKT/mTOR signaling pathway are frequently overexpressed in human epithelial ovarian cancer and are attractive targets for epithelial ovarian cancer therapy." (PMID 23155381, 2012). "In advanced-stage ovarian cancer, the mTOR pathway is upregulated, and hence its blockade will enhance ovarian cancer cell sensitivity to antitumor drugs." (PMID 22481932, 2012). "An in vivo study using xenograft models of ovarian cancer revealed that everolimus inhibited tumor growth, angiogenesis, and production of ascites, suggesting the potential of mTOR inhibitors in the treatment of women with ovarian cancer." (PMID 21961001, 2012). "Several compounds target the PI3K pathway or downstream effectors (e.g. mTOR) and are under early clinical development in epithelial ovarian cancer." (PMID 21799864, 2011). "Lastly, our findings, along with those of others, provide an exciting prospect for using mTOR inhibitors together with other therapies in the treatment of ovarian carcinomas." (PMID 21695255, 2011). "Since PI3K/Akt/mTOR pathway inhibition is reported to decrease invasion and migration of ovarian carcinoma cell lines, thus PPL siRNA potentially decreased cellular attachment, migration or movement at least partly via the PI3K/Akt axis." (PMID 21951621, 2011). "In ovarian cancer, AKT activity is frequently elevated and is closely associated with the upregulation of mTOR signaling." (PMID 20069122, 2010). "An in vivo study using xenografts of SKOV-3 cells revealed that RAD001 inhibited tumor growth, angiogenesis, and production of ascites suggesting the potential of mTOR inhibitors in the treatment of women with ovarian cancer." (PMID 20069122, 2010). "The inhibitory activity of S9 on the PI3K-Akt-mTOR signaling was also confirmed using ovary carcinoma SKOV-3 cells." (PMID 19293927, 2009).
ovarian carcinoma (continued). "As the ovarian tumour cells are known to excrete the endothelial growth factor VEGF-A as well, this suggests an autocrine/paracrine growth factor function of VEGF-A in ovarian cancer through the AKT/mTOR signalling pathway." (PMID 19240722, 2009). "In addition to its role in phenotypic plasticity, miR-6850 also modulated intracellular signaling networks, specifically the PI3K/Akt/mTOR pathway, which is commonly hyperactivated in ovarian cancer." (PMID 41282576, 2026). "The PI3K/AKT/mTOR signaling pathway is the most active and clinically relevant pathway in the management of ovarian cancer as a master regulator of both autophagy and apoptosis, suppressing apoptotic cell death while promoting cytoprotective autophagy under chemotherapeutic stress." (PMID 41595746, 2026). "The activation of PI3K/Akt/mTOR pathway, which is the most often aberrant signalling pathway discovered in 70 % of ovarian cancer cases, is linked to aggressive phenotypes, chemoresistance, and a poor prognosis, making it an important therapeutic target named PI3K/AKT/mTOR inhibitor." (PMID 40179456, 2025). "The experimental results show that the PI3K/AKT/mTOR signaling pathway is inhibited by miR497/TP-HENPs-treated ovarian cancer cells, which reduces the expression of anti-apoptotic proteins, such as Bcl-2 and Bcl-XL, promotes apoptosis and overcomes cell drug resistance." (PMID 40013141, 2025). "DYRK1B seems to be particularly tightly interwoven with this pathway as several points of interaction exist: (i) DYRK1B overexpression promotes mTOR activation and combined inhibition of DYRK1B and mTOR has superior impact on pancreatic and ovarian cancer cell growth compared to single treatment." (PMID 39863750, 2025). "In addition, FBZ can impair microtubule polymerization and inhibit mTOR signaling to suppress ovarian cancer growth." (PMID 40756987, 2025). "Similarly, in ovarian cancer, ATP6V1B1 has been implicated in modulating tumor progression and chemotherapy resistance through the mTOR/autophagy pathway." (PMID 40463372, 2025). "Furthermore, although our results suggest that rapamycin decreases ovarian cancer cell proliferation, the effects of rapamycin and other mTOR inhibitors are still yet to be fully understood." (PMID 40066850, 2025). "The oncogenic pathway of TRPV4 in ovarian cancer may be related to fatty acid synthesis, through the calcium-mTOR/SREBP1 signaling pathway, thereby promoting ovarian cancer progression." (PMID 41465326, 2025). "Recently, HN1 was shown as a regulator of mTOR signalling in ovarian cancer cells." (PMID 39805577, 2025). "This heightened BCAA catabolism may facilitate increased proliferation of ovarian cancer cells through mTOR phosphorylation at the omentum/cancer cell interface." (PMID 40066850, 2025). "Moreover, rapamycin, a well-established inhibitor of mTOR/p70S6K, inhibits resistin-induced ovarian cancer cell proliferation by blocking 70 kDa S6 kinase, which is a key element of mTOR signaling." (PMID 40076482, 2025). "Consequently, targeting the PI3K/AKT/mTOR pathway has become a promising therapeutic strategy in ovarian cancer." (PMID 40395324, 2025). "PI3K/AKT/mTOR pathway is one of the pathways that get altered during ovarian cancer." (PMID 38584538, 2025). "Consequently, it was deduced that ITGB2 has the potential to suppress mitophagy and preserve the steadiness of MMP in ovarian cancer cells via PI3K/AKT/mTOR signaling route." (PMID 38345576, 2024). "In addition, daphnetin is believed to possess antitumor potential, and exhibit potent antitumor effects in ovarian cancer by inducing ROS-dependent apoptosis, which relies on the Akt/mTOR pathway." (PMID 39011506, 2024). "Studies on human breast cancer cells show thatAsiatic acid (AA) in gotu kola plays a role in inducing inhibition of cancer cell growth through mediators such as MAPK, ERK1/2, and p38.Asiatic acid targets P13K/Akt/mTOR to prevent growth and induction of apoptosis in ovarian cancer cells." (PMID 38812527, 2024).